SNORD38C (small nucleolar RNA, C/D box 38C)
Gene: Small nucleolar RNA gene on chromosome 3 (53,333,060 to 53,333,128, reverse strand). Ensembl gene ENSG00000207109.
Gene Ontology:
Biological process: RNA processing
Cellular component: nucleolus
Homologues: Orthologues: chimpanzee SNORD38C (99% identical), macaque SNORD38C (91% identical), mouse Gm22980 (81% identical), rat Snord38b (81% identical). Paralogues in human: SNORD38B (90% identical), SNORD38D (86% identical), SNORD38A (68% identical).